PCSK9 (proprotein convertase subtilisin/kexin type 9)
Diseases named in the same sentence as PCSK9 in open-access papers (continued):
Sharing a sentence is not in itself a finding about the gene and the disease.
Sepsis (continued). "Furthermore, the pharmacological inhibition of PCSK9 using monoclonal anti-PCSK9 antibodies in a murine sepsis model also leads to lower plasma concentrations of inflammatory cytokines and, importantly, significantly increased survival rates." (PMID 31843964, 2020). "The overexpression of PCSK9 reduces LPS clearance and may exacerbate tissue inflammation during sepsis." (PMID 32545766, 2020). "In this review, we summarized the literatures focusing on the roles of PCSK9 in sepsis." (PMID 33123601, 2020). "In sepsis, PCSK9 degraded the low-density lipoprotein cholesterol (LDL) receptors (LDL-R) of the hepatocytes and the very low-density lipoprotein cholesterol receptors (VLDL-R) of the adipocytes, which then subsequently reduced pathogenic lipid uptake and clearance/sequestration." (PMID 33123601, 2020). "In clinical studies, PCSK9 was considered to be crucial for the pathogenesis of sepsis, while inhibiting the PCSK9 activity could effectively improve the prognosis of sepsis." (PMID 33123601, 2020). "Nevertheless, there are still controversies on the roles of PCSK9 in the pathogenesis of sepsis." (PMID 33123601, 2020). "Particularly, the anti-PCSK9 agents under development are mainly focused on the blood lipid metabolism; however, no studies have been conducted to investigate the treatment efficiency of these agents in the setting of bacterial infection and sepsis." (PMID 33123601, 2020). "For instance, the serum PCSK9 level in sepsis patients showed significant elevation, which may be closely related to the subsequent multiple organ failure." (PMID 33123601, 2020). "For illustrative purposes, we show the risk of sepsis, in-hospital mortality, and risk of cardiovascular failure within different tertiles (low, middle, and high) of the PCSK9 GRS and genetically estimated PCSK9 expression levels." (PMID 31509211, 2019). "We hypothesized that PCSK9 LOF variants protect patients with infection from developing sepsis, and, in those who did develop sepsis, that PCSK9 LOF variants would be associated with improved in-hospital survival." (PMID 31509211, 2019). "Whether clearance of Gram positive bacterial lipoteichoic acid (LTA) shows similar dependence on PCSK9, and whether this is clinically relevant in Gram positive human sepsis, is unknown." (PMID 31332258, 2019). "In interim summary, PCSK9 regulates PL clearance and so inhibition of PCSK9 activity is an attractive sepsis and septic shock target - PCSK9 inhibitor(s) could be safe and effective." (PMID 30736368, 2019). "For genetically estimated PCSK9 expression, in the full model adjusted for age, sex, and comorbidities, the odds ratios were 1.01 for sepsis (95% CI, 0.95-1.06; P = .86), 0.96 for cardiovascular failure (95% CI, 0.88-1.05; P = .41), and 0.99 for in-hospital death (95% CI, 0.87-1.14; P = .94)." (PMID 31509211, 2019). "Finally, we measured PCSK9 concentrations in the plasma of critically ill septic and non-septic patients over time to assess the clinical relevance of PCSK9 in sepsis." (PMID 30002483, 2018). "To determine whether PCSK9 levels are affected by sepsis in critically ill patients, we measured plasma PCSK9 concentrations over time in intensive care unit (ICU) patients with sepsis or septic shock from the DYNAMICS study." (PMID 30002483, 2018). "The implications of our study are that inhibition of PCSK9 should be further considered as a novel therapeutic strategy for sepsis, and future research should focus on understanding the systemic effects and clinical outcomes of PCSK9 inhibition in patients with sepsis." (PMID 30002483, 2018). "Recently, studies have suggested that PCSK9 potentiates sepsis-induced mortality." (PMID 28600283, 2017).
Sepsis (continued). "Therefore, when supplementing ω-3 PUFAs for patients with sepsis, the PCSK9 gene background should also be considered, as it may confer greater benefits to patients with specific PCSK9 gene mutations." (PMID 41608459, 2026). "Therefore, early detection of PUFA levels and PCSK9 genotypes, along with the application of ω-3 PUFA nutritional supplements in susceptible populations, may help reduce the risk of developing sepsis." (PMID 41608459, 2026). "Furthermore, sepsis-induced LPS have recently been found to have an upregulating effect on sterol regulatory element-binding protein 2, an important transcription factor of the PCSK9 gene." (PMID 38972879, 2024). "Evidence suggests that PCSK9 inhibition may protect against systemic inflammation and sepsis." (PMID 39051245, 2024). "Theoretically, PCSK9 may predict the prognostic prediction of sepsis." (PMID 37904138, 2023). "Indeed, PCSK9 has been reported as a valuable therapeutic target for sepsis." (PMID 37587410, 2023). "Finally, similar to previous studies, this study did not assess the association between longitudinal PCSK9 changes and prognosis, despite that PCSK9 changes during sepsis have been reported in several studies." (PMID 37904138, 2023). "Indeed, a mice PCSK9-/- model was shown to have lower bacterial numbers in the blood, lungs, and peritoneal fluid than wild-type animals in sepsis models of caecal ligation and perforation, indicating that the deletion of PCSK9 is advantageous for bacterial suppression or clearance." (PMID 37765005, 2023). "Interestingly, increased levels of PCSK9 are a prognostic biomarker in sepsis." (PMID 36361756, 2022). "Lipid clearance by inhibiting PCSK9 may be a new method for the treatment of sepsis." (PMID 36230934, 2022). "In sepsis models of cecal ligation and perforation, PCSK9−/− mice have indeed been reported to have lower bacterial concentrations in the blood, lungs, and peritoneal fluid than wild-type animals, suggesting that deletion of PCSK9 is beneficial for bacterial inhibition or clearance." (PMID 36230934, 2022). "Therefore, it has been hypothesized that, in sepsis, the reduction of cfDNA in PCSK9 knockout mice could reduce coagulopathy." (PMID 34070931, 2021). "Together with the sepsis induced by the Gram-negative bacteria, there were similar findings in the Gram-positive bacteria, in which the 28-day survival in the septic patients with PCSK9 LOF gene mutation was significantly higher than those without." (PMID 33123601, 2020). "Accordingly, PCSK9 might show detrimental effects on immune host response and survival in sepsis." (PMID 33123601, 2020). "Whether PCSK9 could alter outcome in Gram positive human sepsis via this pathway is unknown." (PMID 31332258, 2019). "Similarly, neither the PCSK9 GRS nor genetically estimated PCSK9 expression were significantly associated with sepsis, cardiovascular failure, or in-hospital death in any of the analysis models." (PMID 31509211, 2019). "Therefore, PCSK9 may be a novel therapeutic target for treatment of sepsis, particularly once its mechanistic role in sepsis is elucidated." (PMID 30002483, 2018). "In conclusion, our research results indicate that PCSK9 is a key amplifier of platelet activation and NET formation during sepsis, thereby exacerbating pulmonary microthrombosis." (PMID 41462858, 2025).
Sepsis (continued). "Previous studies have shown that PCSK9 enhances TLR4/MyD88/NF-κB signaling and endothelial dysfunction during sepsis." (PMID 41462858, 2025). "While CRP, PCSK9, ox-LDL and inflammatory cytokines are increased in severe sepsis, systemic sLOX-1 levels have, to our knowledge, not been analysed in sepsis." (PMID 39948564, 2025). "However, the contribution of PCSK9 to pulmonary microthrombosis in sepsis remains unclear." (PMID 41462858, 2025). "The importance of specific lipid and cholesterol metabolism genes including PCSK9, ALOX5, CETP, and DHCR7 in sepsis have been observed." (PMID 39716214, 2024). "In this study, PCSK9 and LDL-C were higher in the two sepsis groups than in the control group (p < 0.05)." (PMID 38972879, 2024). "Consequently, PCSK9 could serve as a promising biomarker for assessing a sepsis prognosis." (PMID 39584843, 2024). "Moreover, a study by Shu and his coworkers in 2023 reported that the 28-day mortality of sepsis increased significantly as the baseline circulating PCSK9 level exceeded 370 ng/ml in their patients, indicating circulating PCSK9 levels may be a potential biomarker to predict the prognosis of sepsis." (PMID 38972879, 2024). "Innate immunity and inflammation, such as ZDHCC19, ALOX15, FCER1A, HDC, PRSS33, and PCSK9, were upregulated in elderly ICU patients with sepsis." (PMID 36823620, 2023). "However, the described positive association of PCSK9 and serum cholesterol is not found in sepsis." (PMID 37515197, 2023). "We found that during sepsis, the elevated miR-15b-5p levels were related to vascular endothelial cell damage, robust inflammation, activation of the NLRP3 pathway, increased PCSK9 levels, and downregulation of SIRT4." (PMID 37587410, 2023). "On day-8 in elderly ICU patients with sepsis, genes related to innate immunity and inflammation, such as ZDHCC19, ALOX15, FCER1A, HDC, PRSS33, and PCSK9, were upregulated." (PMID 36823620, 2023). "PCSK9 has been described to decline in patients with liver cirrhosis, and this was also observed in the SIRS/sepsis cohort studied herein." (PMID 37515197, 2023). "Plasma PCSK9 levels have been shown to serve as a late biomarker of the severity of illness in patients with severe trauma injury in ICU and sepsis and have been correlated to endothelial dysfunction in patients with chronic kidney disease." (PMID 36119052, 2022). "In the two groups of different expression trend modules, the core genes such as CD160, GATA2, GNLY, IL2RB and TGFBR3 were downregulated in the sepsis group, while genes such as ELANE, IL1R1, TLR5, FCGR1A, MAPK14 and PCSK9 were upregulated." (PMID 35332254, 2022). "In this context, proprotein convertase subtilisin/kexin type 9 (PCSK9) inhibitors enhance LDL-mediated elimination of lipopolysaccharide and have shown promise in preclinical studies of sepsis." (PMID 33469739, 2021). "Mice overexpressing PCSK9 show increased levels of thrombin–antithrombin (TAT) complexes, thereby contributing to a hypercoagulable state in sepsis." (PMID 34070931, 2021). "Therefore, PCSK9 may be a potential target for the treatment of sepsis." (PMID 33123601, 2020). "Thus, PCSK9 may serve as a biomarker in the prognosis of sepsis." (PMID 33123601, 2020). "Recently, more attention has been paid to the effects of PCSK9 and VLDL-R on the pathogen lipids in the setting of sepsis." (PMID 33123601, 2020). "Furthermore, although these approaches have previously been successful in other studies, the genetic signal may have been too small to affect the outcomes, and a clinical trial of a drug that inhibits PCSK9 in patients with sepsis could reach different conclusions." (PMID 31509211, 2019).
Sepsis (continued). "Recent studies in a polymicrobial sepsis mouse model using cecal ligation and puncture (CLP) demonstrated that repeated injections of an antibody against PCSK9 in addition to antibiotics were able to decrease the inflammatory response and increase survival." (PMID 28600283, 2017). "Among patients with sepsis or septic shock, those with SARS-CoV-2 infection exhibit higher plasma PCSK9 levels compared to non-infected patients with other causes of severe illness." (PMID 39948564, 2025). "Higher levels of PCSK9 were observed in sepsis patients prescribed statins compared to those with sepsis who did not receive statins." (PMID 41233786, 2025). "While COVID-19 has been associated with elevated PCSK9 levels, sLOX-1 and PCSK9 did not correlate in SIRS/sepsis patients after excluding both, patients with liver cirrhosis and those with COVID-19 (r = -0.080, p = 0.385)." (PMID 39948564, 2025). "In sepsis, the miR-15b-5p–SIRT4 axis may be a target for LPS-induced inflammatory pathways, whereas i-PCSK9 guards against vascular injury." (PMID 41567643, 2025). "Within the severe sepsis group, non-survivors had significantly higher PCSK9 and LDL-C than survivors (p = 0.01 for both)." (PMID 38972879, 2024). "Targeting genes like PCSK9 and DHCR7 could optimize treatments and improve outcomes, paving the way for a precision approach to sepsis management." (PMID 39716214, 2024). "This can be confirmed by the fact that children in our study with sepsis or severe sepsis who developed any organ dysfunction had higher PCSK9 when compared to those who did not suffer organ dysfunction." (PMID 38972879, 2024). "Here, we report on the association between PCSK9 LOF genotype and Angpt-1 in the developing host with sepsis, independent of changes in serum lipoproteins concentrations." (PMID 37365661, 2023). "Consistent with our findings, it has been observed in a sepsis cohort that includes COVID-19 that there is a positive correlation between PCSK9 and CRP, but not with WBC and PCT." (PMID 37904138, 2023). "We are not aware of studies having compared the systemic PCSK9 levels of healthy controls and COVID-19 patients, or COVID-19 patients with and without sepsis." (PMID 37515197, 2023). "COVID-19 sepsis patients had increased plasma PCSK9 levels in comparison to sepsis patients not infected by SARS-CoV-2." (PMID 37515197, 2023). "Of clinical relevance, the 21 COVID-19 patients with sepsis had higher plasma PCSK9 levels in comparison with the SIRS/sepsis patients not infected with SARS-CoV-2." (PMID 37515197, 2023). "In the non-COVID-19 SIRS/sepsis group, patients with Gram-negative and Gram-positive infections had similar plasma PCSK9 levels as patients without a detectable pathogen in their blood." (PMID 37515197, 2023). "Notably, plasma PCSK9 positively correlated with the leukocyte count, procalcitonin, and CRP in patients with SIRS/sepsis and liver cirrhosis." (PMID 37515197, 2023). "Plasma PCSK9 levels of both patient groups did not significantly differ among SIRS/sepsis patients with and without dialysis and patients with and without ventilation." (PMID 37515197, 2023). "Although the majority of studies confirm that PCSK9 is a prognostic factor in sepsis, a number of studies are not concordant." (PMID 36361756, 2022). "Finally, among the highly correlated proteins was PCSK9 that has a central role not only in LDL metabolism but has been shown to promote platelet activation and can be found elevated in sepsis." (PMID 35309299, 2022). "The concentrations of PCSK9 increase transiently over time in critically ill patients both with sepsis and without sepsis, with very similar profiles over 14 days." (PMID 36361756, 2022).
Sepsis (continued). "To date, there are no human trials of PCSK9 inhibition in sepsis, and the only animal study of exogenous PCSK9 inhibition by antibodies to LPS challenge has not shown mortality benefit." (PMID 33920038, 2021). "This implies the potential use of PCSK9 inhibitors to improve outcomes from sepsis, though this has not been tested." (PMID 34018068, 2021). "Our results do not rule out a possible upregulation of PCSK9 in longer or very severe states of inflammation, such as sepsis." (PMID 31843964, 2020). "PCSK9 inhibition should be assessed in sepsis trials of patients who have Gram positive or Gram negative infection." (PMID 31332258, 2019). "PCSK9 inhibitors, which increase LDL clearance, have just been approved to treat certain types of hyperlipidemia but their use is not yet sufficiently prevalent to examine their effect on increased LDL clearance in sepsis." (PMID 29510719, 2018). "While decreased PCSK9 function improves clinical outcomes in murine and human sepsis, the mechanisms involved have not been fully elucidated." (PMID 27171436, 2016). "Therefore, this study aims to investigate the increased expression of PCSK9 in a sepsis mouse model, its subsequent activation of platelets, which in turn triggers NET formation, ultimately leading to the development of sepsis-induced pulmonary microthrombosis." (PMID 41462858, 2025). "Moreover, to our knowledge, this is the first study showing that COVID-19 sepsis patients have higher plasma PCSK9 levels compared to healthy controls and in comparison with sepsis patients not infected with SARS-CoV-2." (PMID 37515197, 2023). "Finally, i-PCSK9 enhanced the ability of i-miR-15b to restore the SIRT4 protein levels (p < 0.05 versus i-miR-15b + LPS), indicating the pivotal role of the miR-15b-5p–SIRT4 axis in endothelial dysfunction under sepsis." (PMID 37587410, 2023). "PCSK9 is also involved in the degradation of the VLDL receptor and adipose tissue may play a secondary role in the removal of lipopolysaccharide via VLDL receptor uptake, which may explain why sepsis prognosis is better in obese patients." (PMID 36361756, 2022). "This has important implications in health as strategies aimed at inhibiting PCSK9 function may be an effective treatment option for both Gram-positive and negative sepsis." (PMID 31332258, 2019). "The profile of PCSK9 concentrations over time was strikingly similar in septic and non-septic critically ill patients, demonstrating that elevations in PCSK9 concentrations due to critical illness are not specific to sepsis." (PMID 30002483, 2018). "PCSK9 inhibitors are currently under investigation as lipid-lowering agents because they promote LDL clearance and thus reduce LDL levels, but they may also have an application in clearance of lipid-based pathogens in sepsis." (PMID 28010729, 2016). "However, other investigations do not support a role of PCSK9 in sepsis." (PMID 37515197, 2023). "Therefore, the use of PCSK9 inhibitors during sepsis is unknown, and the preventive effect of PCSK9 inhibitors on sepsis cannot be ruled out." (PMID 36230934, 2022). "However, there are no studies focused on the treatment of sepsis using PCSK9 in clinical settings." (PMID 33123601, 2020). "In another study, PCSK9 could affect the pathogen lipid clearance and the secretion of downstream inflammatory factors through binding with LDL-R and the subsequent lysosome degradation in the sepsis and septic shock patients, which finally affected the prognosis of sepsis patients." (PMID 33123601, 2020). "However, the exact roles of PCSK9 in the pathogenesis of sepsis are still not well defined." (PMID 33123601, 2020).